MFN1 (mitofusin 1)
Diseases named in the same sentence as MFN1 in open-access papers (continued):
Sharing a sentence is not in itself a finding about the gene and the disease.
Cerebral ischemia (2 papers, 2023 to 2025). Restriction of arterial blood supply to the brain associated with insufficient oxygenation to support the metabolic requirements of the tissue. "Cerebral ischemia–reperfusion induces mitochondrial dynamics disorders, upregulates the expression of the mitochondrial division protein Fis 1, and inhibits the expression of mitochondrial fusion proteins MFN1, MFN2, and OPA1, while 14, 15‐EET treatment reverses this process." (PMID 37017405, 2023). "Immunofluorescence results showed that the expression levels of Mfn1, Mfn2, and OPA1 were downregulated in mouse cerebral cortex after cerebral ischemia–reperfusion, while 14, 15‐EET treatment reversed this protein downregulation." (PMID 37017405, 2023). "Our study showed that the expression levels of MFN1, MFN2, and OPA1 protein were downregulated after cerebral ischemia–reperfusion, and 14, 15‐EET treatment inhibited the downregulation of these proteins and promoted mitochondrial fusion." (PMID 37017405, 2023).
Charcot-Marie-Tooth disease type 2A (2 papers, 2020 to 2022). "Strikingly, mutations in MFN2 but not MFN1 can cause Charcot-Marie-Tooth disease type 2A (CMT2A), a peripheral neuropathy characterized by axonal degeneration." (PMID 32595603, 2020).
cognitive deficit (2 papers, 2021 to 2025). "Furthermore, clinical evidence has revealed that Mfn1 was decreased in AD patients and this decrease correlated with cognitive deficit." (PMID 34572135, 2021).
colitis (2 papers, 2022 to 2025). Inflammation of the colon. "MFN1, MFN2, OPA1, and p-DRP1 levels increased in a model of DSS-induced colitis." (PMID 35035669, 2022). "However, both Fis1 and Mfn1 were not effectively upregulated in KOIEC mice during DSS-induced colitis." (PMID 40089459, 2025).
emphysema (2 papers, 2022 to 2023). "Reduced expression of MFN1, MFN2 and OPA1 were also seen in alveolar epithelial cells in emphysema/COPD patients." (PMID 38110986, 2023). "The degree of impaired mitochondrial fission/fusion as suggested by reduced expression of mitofusin 1 (MFN1), optic atrophy 1 (OPA1), Fission, Mitochondrial 1 (FIS1) and phosphorylated dynamin-related protein 1 (p-DRP1) correlated with level of emphysema." (PMID 35820851, 2022).
fatty liver disease (2 papers, 2022 to 2023). A reversible condition wherein large vacuoles of triglyceride fat accumulate in liver cells via the process of steatosis. "The study found that the expression level of MFN2 protein decreased significantly in NASH patients, liver steatosis mice and NASH mice; another study found that MFN1 protein expression was significantly reduced in the liver of NAFLD mice." (PMID 36676939, 2022).
Glucose intolerance (2 papers, 2022 to 2023). Glucose intolerance (GI) can be defined as dysglycemia that comprises both prediabetes and diabetes. "In contrast, double knockout mice with β cell-specific Mfn1 and 2 deletions displayed glucose intolerance and impaired insulin secretion due to loss of mtDNA content." (PMID 37762083, 2023). "Our observations showing distinct and overlapping contributions of Mfn1 and 2 in the regulation of β-cell mitochondrial function led us to hypothesize that loss of mitochondrial fusion would lead to glucose intolerance due to mtDNA depletion." (PMID 35487893, 2022). "Consistently, the pancreatic β cell-specific knockout of Mfn1/2 in mice (βMfn1/2 KO) led to several metabolic abnormalities, such as glucose intolerance, impaired glucose clearance, and a decrease in plasma insulin levels." (PMID 37762083, 2023). "We additionally confirmed reductions in Tfam and increases in LonP1 protein in β-Mfn1+/−Mfn2KO islets, correlating with the mtDNA depletion, glucose intolerance, and impaired GSIS observed in these mice." (PMID 35487893, 2022). "To evaluate other etiologies of glucose intolerance in β-Mfn1/2DKO mice, we first measured β-cell mass." (PMID 35487893, 2022). "Despite mitochondrial morphologic imbalances in both β-Mfn1+/−Mfn2KO and β-Mfn1KOMfn2+/− mice, only β-Mfn1+/−Mfn2KO mice developed glucose intolerance and impaired GSIS similar to that of β-Mfn1/2DKO mice." (PMID 35487893, 2022). "Our single allele mouse models directly demonstrate that Mfn1/2-deficiency is coupled to glucose intolerance through mtDNA loss rather than mitochondrial structure." (PMID 35487893, 2022). "However, combined deletion of both Mfn1 and Mfn2 resulted in severe glucose intolerance (p < 0.005 by one-way ANOVA vs. Ctrl), due to markedly reduced GSIS." (PMID 35487893, 2022). "Whereas Mfn1 and Mfn2 individually were dispensable for glucose homeostasis, combined Mfn1/2 deletion in β-cells reduced mtDNA content, impaired mitochondrial morphology and networking, and decreased respiratory function, ultimately resulting in severe glucose intolerance." (PMID 35487893, 2022).
HCMV infection (2 papers, 2022 to 2023). "In this study, we found that HCMV infection caused mitochondrial fusion, and expression of mitofusin 1 (MFN1), which is a protein associated with mitochondrial antiviral signaling protein (MAVS), positively regulates mitochondrial fusion and HCMV-induced IFN1 response." (PMID 36939338, 2023). "Thus, we hope to investigate the function of MFN1 protein during HCMV infection and its association with IFN1 production." (PMID 36939338, 2023). "As viral infection could cause mitochondrial fusion fission imbalance, and MFN1 is a GTPase protein located on the outer membrane of mitochondria, its expression is increased in HCMV infection, which may be involved in the localization of MAVS." (PMID 36939338, 2023). "However, the underlying mechanism of MFN1’s promotion of IFN1 during HCMV infection still remains unknown." (PMID 36939338, 2023). "Meanwhile, HCMV infection upregulated the expression levels of MFN1 and OPA1 and overlapped with the M-AAA protease 1 homolog (OMA1)." (PMID 36939338, 2023). "In the present study, human monocytic macrophage THP-1 was used as cell model for HCMV infection and changes in interferon signal pathway and mitochondrial morphology, MFN1, and MAVS were detected." (PMID 36939338, 2023). "In conclusion, we provide new insight into the relationship between MFN1 and IFN1 during HCMV infection and show that MFN1 may serve as a potential strategy against HCMV infection." (PMID 36939338, 2023). "We aimed to illustrate the role of MFN1 in IFN response in HCMV infection." (PMID 36939338, 2023). "In addition, the redistribution of MAVS was induced by HCMV infection, whereas the knockdown of MFN1 inhibited the redistribution of MAVS and disrupted the interferon signaling pathway." (PMID 36939338, 2023). "Moreover, HCMV infection upregulated the expression levels of MFN1 in human monocytes." (PMID 36939338, 2023). "In addition, we detected the expression of MFN1 of monocytes in patients with HCMV infection." (PMID 36939338, 2023). "In summary, our study provides new insight into the relationship between MFN1 and IFN1 during HCMV infection, with regulating of the balance between mitochondrial dynamics and IFN1 proven to be critical." (PMID 36939338, 2023). "The expression levels of mitochondrial fusion-related proteins including MFN1, OPA1, and OMA1 were increased in HCMV-infected THP-1 cells, as well as mitochondrial fusion after HCMV infection." (PMID 36939338, 2023). "HCMV infection promoted IFN1 production and induced the expression of MFN1 in THP-1 cells and human monocytes." (PMID 36939338, 2023). "HCMV infection regulated IFN1 expression through mitochondrial dynamics, whereas MFN1-knockdown THP cells induced mitochondrial fission and suppressed ISGs transcription and protein expression." (PMID 36939338, 2023). "The results showed that the expression of genes regulating mitochondrial fusion (MFN1 and MFN2) was decreased after HCMV infection, while the expression of genes regulating mitochondrial division (Drp1 and FIS1) was upregulated." (PMID 35359726, 2022).
HIV-1 infection (2 papers, 2024 to 2025). The type species of lentivirus and the etiologic agent of acquired immunodeficiency syndrome (AIDS). "Furthermore, human immunodeficiency virus type 1 (HIV-1) infection increased Mfn1 and Mfn2 protein levels, protecting against MMP depolarization, which contributes to inhibiting apoptosis and supporting viral proliferation." (PMID 40284870, 2025).
liver cancer (2 papers, 2022 to 2025). An epithelial or non-epithelial malignant neoplasm that arises from the liver. "In the tumor tissues of liver cancer patients, larger mitochondria were observed, accompanied with raised expression of OPA1 and Mfn1, indicating enhanced mitochondrial fusion in tumor tissues, which promoted metabolism and tumor growth." (PMID 40500258, 2025). "In contrast to MFN1, knockout of MFN2 in liver causes a nonalcoholic steatohepatitis (NASH)-like phenotype and liver cancer, suggesting noncomplementary roles of MFN1 and MFN256." (PMID 35710796, 2022).
myopia (2 papers, 2008 to 2010). "Furthermore, single nucleotide polymorphisms in the mitofusin-1 (MFN1) and presenilin associated rhomboid-like (PSARL) genes are among the clustering peak showing a genetic association with myopia that was mapped to 3q26 (MYP8 locus)." (PMID 20208987, 2010). "We are confident that additional mapping studies for these data are likely to replicate further candidate genes at 3q26-28 and genome-wide, which along with MFN1 and PSARL, can be taken forward to clarify the molecular genetic aetiology of common myopia." (PMID 18846214, 2008).
nasopharyngeal carcinoma (2 papers, 2020 to 2021). A carcinoma arising from the nasopharyngeal epithelium. "However, in nasopharyngeal carcinoma tissues, hypoxia causes T-cells exhaustion by reducing their energetic metabolism through an MFN1 (Mitofusin 1) down-regulation via a miR-24 dependent repression of the MYC transcription factor." (PMID 34539584, 2021).
optic atrophy (2 papers, 2021 to 2025). A disorder characterized by loss of optic nerve fibers. "Interestingly, we found a significant increase in the expression of mitochondrial fusion proteins, including mitofusin 1 and 2 (MFN1/2) and optic atrophy (OPA), in OECM‐1 CSCs after 6 and 16 h hypoxia exposure compared with similarly treated OECM‐1 cells." (PMID 39945227, 2025).
retinal degeneration (2 papers, 2018 to 2023). Degeneration of the retina. "When the Mfn1/Mfn2 ratio and the mitochondrial fusion/fission are imbalanced, it will induce retinal degeneration using mitophagy." (PMID 38001811, 2023).
schizophrenia (2 papers, 2024 to 2025). A major psychotic disorder characterized by abnormalities in the perception or expression of reality. "This editing site has been recently detected in brain samples in context of schizophrenia and was shown to affect MFN1 function in mitochondrial fusion." (PMID 40813454, 2025). "During our study on CLL, another team reported S329L MFN1 editing in brain samples and hypoediting of this site in samples from schizophrenia patients." (PMID 40813454, 2025). "Finally, we identified CSNK2B, TOMM40, MAP1LC3B, MFN1, CSNK2A2, PGAM5 and ATG12 as the diagnostic genes for schizophrenia." (PMID 39355378, 2024).
Sepsis (2 papers, 2022 to 2024). Sepsis is defined as life-threatening organ dysfunction caused by a dysregulated host response to infection. "Our results showed that the expression of Drp1 and Fis1 was increased, while OPA1, Mfn1 and Mfn2 were decreased in the intestinal epithelium during sepsis, indicating increased mitochondrial fission and insufficient mitochondrial fusion." (PMID 36581806, 2022). "Western blot analysis revealed that in the LPS-induced sepsis model (Group 2), Nogo-A expression was significantly elevated, while the expression of proteins such as p-PERK, MFN1, NOX2, NOX4, NLRP3, p-STING, p-TBK1, and IL-1β also significantly increased, and SHP2 expression decreased." (PMID 39151100, 2024).
ZIKV infection (2 papers, 2020). "Although ZIKV infection still shortened mitochondrial branch length in cells overexpressing MFN1 or MFN2, the range of branch lengths in these cells was similar to uninfected controls." (PMID 33424801, 2020). "To further explore if blocking mitochondrial fragmentation would help increase cell survival after ZIKV infection, we over-expressed both MFN1 and MFN2 to restore normal fusion and treated cells with Mdivi-1 to inhibit DNM1L activity, reducing mitochondrial fission." (PMID 33424801, 2020). "In correlation with the sequencing results, qRT-PCR data also show increased expression levels of MFN1 and OPA1 following ZIKV infection." (PMID 32902370, 2020). "The mitochondrial networks were only spared in MFN2 and not MFN1 overexpressing cells after ZIKV infection." (PMID 33424801, 2020).
Alzheimer disease (1 paper, 2025). A progressive, neurodegenerative disease characterized by loss of function and death of nerve cells in several areas of the brain leading to loss of cognitive function such as memory and language. "For instance, in neurons from the hippocampus of Alzheimer’s disease patients, reduced expression of Opa1, Mfn1/2, and Drp1, along with increased Fis1 levels, has been observed." (PMID 41465333, 2025).
brain injury (1 paper, 2021). Acute and chronic (see also brain INJURIES, CHRONIC) injuries to the brain, including the cerebral hemispheres, CEREBELLUM, and brain STEM. "Regarding the effects of Mdivi-1 on neural mitochondrial fusion, the included studies showed that Mdivi-1 only increased neural outer membrane mitochondrial fusion (e.g., Mfn1 factor) but did not affect the neural inner membrane mitochondrial fusion (e.g., Opa1 factor) in I/R-induced brain injury." (PMID 35002619, 2021).
cerebellar degeneration (1 paper, 2010). Degeneration of the cerebellum. "The fundamental importance of mitochondrial remodelling in mammalian pathophysiology has been underlined by in utero lethality and cerebellar degeneration in mice with homozygous mutations in Dnm1l itself, as well as Mfn1, Mfn2, or Opa1." (PMID 20585624, 2010).
cervical cancer (1 paper, 2023). A primary or metastatic malignant neoplasm involving the cervix. "In addition, RNA sequencing data showed that Sp1 expression was positively correlated with the expression of Mfn1/2, Opa1, and Drp1 in tissues of cervical cancer patients." (PMID 37147632, 2023).
cholangiocarcinoma (1 paper, 2021). A carcinoma that arises from the intrahepatic biliary tree (intrahepatic cholangiocarcinoma) or from the junction, or adjacent to the junction, of the right and left hepatic ducts (hilar cholangiocarcinoma). "Studies have shown that the downregulation of OPA1 or MFN1 inhibit the fusion process of HCC cell lines and cholangiocarcinoma (CCA) tumor organoids, inhibiting the growth of tumors in the body." (PMID 34804779, 2021).
colon adenoma (1 paper, 2019). An adenoma that arises from the colon. "In accordance to this, ApcMin/+ mice, which develop spontaneous intestinal and colon adenomas, showed diminished MFN1, MFN2 and PGC-1α protein expression in advance to the decrease of muscle mitochondrial content." (PMID 31466311, 2019).
deficiencies (1 paper, 2018). "Deletion of Mfn1 and Mfn2 in skeletal muscle results in reduction of mtDNA and respiratory deficiencies." (PMID 30333037, 2018).
Endometrial Cyst (1 paper, 2023). It is caused by endometriosis, and formed when a tiny patch of endometrial tissue (the mucous membrane that makes up the inner layer of the uterine wall) bleeds, sloughs off, becomes transplanted, and grows and enlarges inside the ovaries. "Increased oxidative stress and ROS accumulation have been found in serum, peritoneal fluid, and ectopic endometrial cysts in patients with endometriosis, which can reduce the expression of MFN1, MFN2, and OPA1, compatible with our result." (PMID 37393390, 2023).
endometriosis (1 paper, 2023). The growth of functional endometrial tissue in anatomic sites outside the uterine body. "Here, we demonstrated a decline in mRNA and protein expression levels of DRP1, OPA1, MFN1, and MFN2 in ectopic ESCs and tissue and a decrease in mitochondrial number in endometriosis." (PMID 37393390, 2023).
fertility disorders (1 paper, 2025). "Our results suggest that MFN1 may serve as a valuable therapeutic target for alleviating fertility disorders and age‐related declines in female reproduction." (PMID 40091361, 2025).
fluorosis (1 paper, 2025). "Mfn1 protein and mRNA expression was evidently decreased in the renal tissues of rats with chronic fluorosis, but Fis1 expression was increased." (PMID 39896143, 2025).
gingivitis (1 paper, 2025). A disorder involving inflammation of the gums; may affect surrounding and supporting structures of the teeth. "The MERC protein MFN1 may contribute to the etiology of periodontal disease, as evidenced by its elevated levels in the gingival crevicular fluid of patients with periodontitis and gingivitis." (PMID 39896143, 2025).
hyperhomocysteinemia (1 paper, 2023). A serious metabolic condition caused by mutations in the MTHFR gene, medications, or nutritional deficiency. "In the hyperhomocysteinemia rat model, the mitophagy‐related proteins FUN14 domain containing 1 and LC3B and the mitochondrial fusion proteins Mfn1 and Mfn2 are down‐regulated, whereas expression of the mitochondrial fission protein Drp1 is up‐regulated." (PMID 37208948, 2023).
Hypertonia (1 paper, 2018). A condition in which there is increased muscle tone so that arms or legs, for example, are stiff and difficult to move. "By using co-immunoprecipitation analyses, we found that endogenous Trak1 specifically interacted with Mfn1 and Mfn2 but not with Drp1 and that the ability of Trak1 to interact with mitofusins was not affected by hypertonia-associated mutation." (PMID 28924745, 2018).
hyperuricemia (1 paper, 2025). An abnormally high level of uric acid. "To investigate the mechanisms of hyperuricemia-related cardiovascular diseases, we examined the expression of mitochondrial fission 1 protein (FIS1), as well as mitofusin 1 (MFN1) and mitofusin 2 (MFN2), which are key regulators of mitochondrial fusion." (PMID 40361044, 2025).
hypogonadism (1 paper, 2021). A disorder characterized by decreased function of the gonads. "Moreover, hypogonadism was found to affect mitofusin (Mfn1) and mitofusin (Mfn2) in the Leydig cells by reducing the transcription of Drp1, as well as Mfn1 and Mfn2, without changing protein optic atrophy 1 (Opa1) levels." (PMID 34440620, 2021).
Leigh syndrome (1 paper, 2023). A progressive neurological disease defined by specific neuropathological features associating brainstem and basal ganglia lesions. "Given that mutations in LRPPRC result in Leigh syndrome, it is likely that Ben/Ubc13-PINK1-Park may regulate Mfn1 and Mfn2 in Leigh syndrome as well in other mitochondrial diseases." (PMID 37098042, 2023).
liver fibrosis (1 paper, 2022). "Last but not least, Mfn1 and Opa1 were downregulated in schistosomiasis-induced liver fibrosis, and lipoic acid treatment upregulated Mfn1 and Opa1 and alleviated fibrosis." (PMID 35933403, 2022).
lung diseases (1 paper, 2025). "Furthermore, the age‐related mtDNA damage in lung diseases tends to upregulate mitochondrial fusion‐related proteins such as MFN1 and optic atrophy‐1 protein (OPA1) to compensate mitochondrial deficiencies." (PMID 39668579, 2025).
medulloblastoma (1 paper, 2025). A malignant, invasive embryonal neoplasm arising from the cerebellum. "In medulloblastoma, sonic hedgehog signaling was shown to induce mitochondrial fragmentation through induction of Drp1 and suppression of the pro-fusion proteins, MFN1/2, in vitro and in vivo." (PMID 41473749, 2025).
migraine (1 paper, 2025). "When mitochondrial dynamics are examined, migraine models frequently exhibit the upregulation of fission-related genes such as Drp1 and Fis1, along with the downregulation of fusion-related genes like Mfn1." (PMID 40868921, 2025).